DEPDC1B (DEP domain containing 1B)
Diseases named in the same sentence as DEPDC1B in open-access papers (continued):
Sharing a sentence is not in itself a finding about the gene and the disease.
prostate carcinoma (10 papers, 2020 to 2023). A carcinoma that arises from epithelial cells of the prostate gland. "On the other hand, DEPDC1B is identified as a new diagnostic and prognostic biomarker of hepatocellular carcinoma and prostate cancer, which has significant clinical value." (PMID 36568241, 2022). "DEPDC1B positively correlates with prostate cancer metastasis, tumor stage, Gleason score, and poor prognosis." (PMID 33135357, 2020). "Furthermore, DEPDC1B mRNA was an independent prognostic factor for biochemical recurrence‐free survival in prostate cancer patients." (PMID 37056386, 2023). "In addition, the expression of DEPDC1B was dramatically increased in prostate cancer tissues compared with normal prostate tissues." (PMID 37056386, 2023). "They proposed that DEPDC1B level could be used as an independent predictor of the biochemical relapse-free survival time of patients with prostate cancer." (PMID 34983303, 2022). "DEPDC1B has been identified as a prostate cancer metastasis oncogene." (PMID 35757968, 2022). "A similar study further proved that DEPDC1B may affect the prognosis of patients with prostate cancer through the regulation of autophagy." (PMID 35095994, 2021). "However, only NEIL3, CEP55, and DEPDC1B had a significant relationship with the prognosis of prostate cancer." (PMID 34591415, 2021). "In pancreatic cancer or prostate cancer, DEPDC1B could promote migration and invasion through Rac1/PAK1 signaling." (PMID 34330893, 2021). "In addition, DEPDC1B is required for a variety of malignancies, such as breast cancer, non-small cell lung cancer, oral cancer, prostate cancer, melanoma, and glioblastoma." (PMID 34330893, 2021). "DEPDC1B enhances prostate cancer cell metastasis and tumor growth in vitro and in vivo." (PMID 33135357, 2020).
bladder cancer (9 papers, 2020 to 2024). "The upregulated expression of DEPDC1B was observed in tumor tissues of bladder cancer and DEPDC1B high expression was found to be associated with advanced malignant grade." (PMID 33203836, 2020). "A recent study also showed that upregulated SHC1 expression could act as a tumor promoter in bladder cancer and an underlying downstream of DEPDC1B." (PMID 35601500, 2022). "Related investigations reported that DEPDC1B is overexpressed in various cancer types, such as breast cancer, oral cancer, non-small-cell lung cancer, melanoma cancer, bladder cancer and prostate cancer." (PMID 35706026, 2022). "This association was further confirmed by Spearman rank correlation analysis, thus indicating the potential role of DEPDC1B in the development and progression of bladder cancer." (PMID 33203836, 2020). "To investigate the synergistic effect of DEPDC1B and SHC1 on bladder cancer, we constructed T24 cells that overexpressed DEPDC1B, and T24 cells that simultaneously overexpressed DEPDC1B but with the KD of SHC1." (PMID 33203836, 2020). "Given the high expression levels of DEPDC1B in bladder cancer cells, we selected EJ and T24 cell lines for the construction of DEPDC1B KD cell models." (PMID 33203836, 2020). "The suppression of bladder cancer by DEPDC1B was executed through inhibiting cell proliferation, cell migration, and promoting cell apoptosis." (PMID 33203836, 2020). "Gene expression profiling data acquired from The Cancer Genome Atlas also demonstrated the clear upregulation of DEPDC1B expression in bladder cancer tissues (with a fold change of 7.94, P < 0.001)." (PMID 33203836, 2020). "All the results showed the role of SHC1 as a tumor promotor in bladder cancer and a potential downstream of DEPDC1B." (PMID 33203836, 2020). "Collectively, these results demonstrated that levels of DEPDC1B are elevated in bladder cancer and highlighted the potential role of DEPDC1B as a tumor promotor." (PMID 33203836, 2020). "All these results recognized DEPDC1B as a tumor promotor in the development and metastasis of bladder cancer." (PMID 33203836, 2020). "The analysis of clinical specimens revealed the upregulated expression of DEPDC1B in bladder cancer, which was positively related to tumor grade." (PMID 33203836, 2020). "In this study, we found that DEPDC1B was upregulated in tumor tissues of bladder cancer and related with malignant grade." (PMID 33203836, 2020). "Through RNA sequencing, the potential downstream of DEPDC1B in the regulation of bladder cancer was screened and SHC1 was identified as the most promising candidate." (PMID 33203836, 2020). "To explore the role of DEPDC1B in bladder cancer, we used IHC to detect the expression levels of DEPDC1B in tumor tissues collected from bladder cancer patients and compared these levels with those from normal tissues." (PMID 33203836, 2020). "SHC1 is an essential molecule that DEPDC1B regulates the evolution of bladder cancer progression." (PMID 35903358, 2022). "SHC1 knockout can reduce the effect of DEPDC1B on bladder cancer induction." (PMID 35903358, 2022). "Moreover, we also used qPCR to determine the background expression of DEPDC1B in various bladder cancer cell lines (EJ, T24, J82, and RT4); this analysis demonstrated high expression levels of DEPDC1B in all cells DEPDC1B." (PMID 33203836, 2020). "Knockdown (KD) of DEPDC1B could inhibit the development and progression of bladder cancer in vitro and in vivo." (PMID 33203836, 2020). "In vitro and in vivo studies showed that DEPDC1B knockdown could inhibit the growth of bladder cancer cells or xenografts in mice." (PMID 33203836, 2020). "In this study, we aimed to explore the functions and mechanism of DEPDC1B in bladder cancer." (PMID 33203836, 2020). "Furthermore, the role of DEPDC1B in bladder cancer was also proved by in vivo experiments, which showed significantly restrained tumor growth of bladder cancer upon DEPDC1B KD." (PMID 33203836, 2020).
bladder cancer (continued). "In conclusion, DEPDC1B was identified as a key regulator in the development of bladder cancer, which may be used as a potential therapeutic target in the treatment of bladder cancer." (PMID 33203836, 2020). "Although the role of DEPDC1B in the progression of various types of cancers have been understood, whether DEPDC1B could affect bladder cancer remains to be elucidated." (PMID 33203836, 2020). "Therefore, the regulation of bladder cancer by DEPDC1B through SHC1 make it a potential therapeutic target for bladder cancer treatment." (PMID 33203836, 2020). "In summary, RNA sequencing indicated that DEPDC1B may regulate the development of bladder cancer by targeting SHC1." (PMID 33203836, 2020). "Collectively, these results proved that DEPDC1B KD could suppress the development and progression of bladder cancer in vitro." (PMID 33203836, 2020). "More importantly, SHC1 KD could attenuate DEPDC1B overexpression-induced promotion of bladder cancer." (PMID 33203836, 2020). "This study aimed to explore the role and mechanism of DEPDC1B in the development of bladder cancer." (PMID 33203836, 2020). "Moreover, KD of DEPDC1B significantly inhibited cell proliferation of bladder cancer, and promoted cell apoptosis through the regulation of Caspase-3, clAP-2, IGF-I, IGFBP-2, IGF-1sR, Livin, TNF-β, TRAILR-3, and TRAILR-4." (PMID 33203836, 2020). "Therefore, the KD of SHC1 exhibited similar inhibitory effects on bladder cancer as DEPDC1B KD." (PMID 33203836, 2020). "Moreover, a mechanistic study found that SHC1 may be an important route through which DEPDC1B regulates the development of bladder cancer." (PMID 33203836, 2020). "To further investigate the role of SHC1 in bladder cancer, we constructed a SHC1 KD cell model and verified thus using the method described for DEPDC1B KD DEPDC1B." (PMID 33203836, 2020). "In conclusion, we found the upregulated expression of DEPDC1B and SHC1 in tumor tissues of bladder cancer." (PMID 33203836, 2020). "More importantly, the investigation of the synergistic effects of DEPDC1B and SHC1 on bladder cancer showed that SHC1 KD could alleviate or even reversed the regulation of bladder cancer by DEPDC1B overexpression." (PMID 33203836, 2020). "Both DEPDC1B and SHC1 could act as tumor promotor in the development and progression of bladder cancer, through regulating cell proliferation, colony formation, cell apoptosis and cell migration." (PMID 33203836, 2020).
hepatocellular carcinoma (9 papers, 2014 to 2025). A malignant tumor that arises from hepatocytes. "Through the analysis of liver hepatocellular carcinoma (LIHC)-related data in the TCGA dataset, the result identified DEPDC1B was a pivotal protein highly associated with histological grade of HCC." (PMID 34983303, 2022). "Actually, CDK1 was also found to be a downstream effector in the DEPDC1B-related regulation of hepatocellular carcinoma." (PMID 36568241, 2022). "Relationship between DEPDC1B expression and tumor characteristics in patients with hepatocellular carcinoma." (PMID 34032605, 2021). "DEPDC1B-expressing hepatoma cells exhibited a substantially increased invasion rate compared with the parental cells." (PMID 25091805, 2014). "Overexpressed DEPDC1B contributes to the progression of hepatocellular carcinoma by CDK1." (PMID 35706026, 2022). "The study confirmed that DEPDC1B is overexpressed in hepatic carcinoma tissues, and the development of HCC were regulated by DEPDC1B through controlling cell apoptosis, inducing G2 phase arrest, migration, and proliferation." (PMID 34032605, 2021).
lung carcinoma (6 papers, 2022 to 2025). "Our study demonstrated the diagnostic role of DEPDC1B autoantibody in early lung cancer, and there may be some unknown mechanism that prevents the generation of DEPDC1B autoantibody and leads to tumor progression." (PMID 39949782, 2025). "The roles of DEPDC1B have been fully studied, and consistent with our conclusion, DEPDC1B promotes malignant in various types of tumors including lung cancer." (PMID 39949782, 2025). "Like DEPDC1B, KIF23 was overexpressed in various cancers, such as pancreatic cancer, breast cancer and primary lung cancer." (PMID 34983303, 2022). "During our analysis, increased expressions of PCDH7, DEPDC1B, SATB2, and S100P were detected in lung cancer tissues and adjacent normal tissue of TCGA-LUAD patients, but expression of FGD3 was observed to be lower." (PMID 36530971, 2022).
pancreatic cancer (6 papers, 2020 to 2022). "Consistently, DEPDC1B was able to promote migration and invasion of pancreatic cancer cell through Rac1/PAK1-LIMK1-Cofilin1 pathway." (PMID 35706026, 2022). "Furthermore, a previous report indicating the role of DEPDC1B in pancreatic cancer development through targeting the Akt/Gsk3b/Snail pathway also provides support for the alleviation of DEPDC1B overexpression-induced effects by CDK1 knockdown." (PMID 36568241, 2022). "In addition, DEPDC1B promotes the migration and invasion of pancreatic cancer through the Rac1/PAK1-LIMK1-Cofilin1 signal pathway." (PMID 36568241, 2022). "Moreover, DEPDC1B was found to be able to promote migration and invasion of pancreatic cancer through Rac1/PAK1-LIMK1-Cofilin1 signal pathway." (PMID 33203836, 2020).
breast carcinoma (5 papers, 2020 to 2023). "Here, we found that DEPDC1B was highly expressed in breast cancer cells and tissues and was associated with lower overall survival (OS) in patients." (PMID 37642235, 2023). "Further tissue microarray analysis showed that the high expression of DEPDC1B was an independent risk factor for poor prognosis in breast cancer patients." (PMID 37642235, 2023). "More noteworthy is that univariate and multivariate Cox regression analyses showed that high expression of DEPDC1B was an independent risk factor for poor prognosis in breast cancer patients." (PMID 37642235, 2023). "Previous profiling of DEPDC1B mRNA in MDA-MB 231 breast cancer cells showed that it was associated with decreased cell death and increased cell proliferation." (PMID 32684847, 2020). "In addition, in breast cancer patients high DEPDC1B levels were associated with shorter overall survival (OS)." (PMID 37642235, 2023). "In addition, we also found that high DEPDC1B expression is an independent risk factor for breast cancer patients, leading to worse OS." (PMID 37642235, 2023). "Here, we proved that interference with DEPDC1B expression can significantly inhibit the metastasis of breast cancer cells in vivo and in vitro." (PMID 37642235, 2023). "What is more noteworthy is that there is no change of SCUBE3 expression in interference or overexpression of DEPDC1B in breast cancer cells in vitro." (PMID 37642235, 2023). "Here, we found that DEPDC1B was highly expressed in breast cancer tissues and cells compared with normal tissues and cells." (PMID 37642235, 2023). "High expression level of DEPDC1B in MDA-MB-231 human breast cancer cells was correlated with enhanced p-ERK expression, cell proliferation and cell survival." (PMID 37056386, 2023). "Through online tool analysis, we found that DEPDC1B is highly expressed in a variety of tumor cells, including a variety of breast cancer cell lines, which is consistent with our cell test results." (PMID 37642235, 2023). "Our findings provide new insights into the carcinogenic mechanism of DEPDC1B, suggesting that DEPDC1B can be considered a potential therapeutic target for breast cancer." (PMID 37642235, 2023). "In contrast, DEPDC1B overexpression significantly promoted the migration and invasion of breast cancer cells and promoted the EMT process in cells." (PMID 37642235, 2023). "Our results confirmed that DEPDC1B activated the wnt/β-catenin signaling pathway in breast cancer cells." (PMID 37642235, 2023). "It is worth noting that our study proved for the first time that there is a high correlation between DEPDC1B and breast cancer cell metastasis." (PMID 37642235, 2023). "At the same time, high DEPDC1B expression was associated with shorter distant metastasis-free survival (DMFS), disease-free survival (DFS), and OS in breast cancer patients." (PMID 37642235, 2023). "Our results show that DEPDC1B is upregulated in breast cancer tissues and cells, which promotes cell metastasis by promoting the EMT process of cells." (PMID 37642235, 2023). "Mechanistically, DEPDC1B was first shown to activate the wnt/β-catenin signaling pathway as an oncogene in breast cancer cells." (PMID 37642235, 2023). "In summary, these data show that DEPDC1B was upregulated in breast cancer tissues and cells and high DEPDC1B expression was highly predictive of poor prognosis in breast cancer patients." (PMID 37642235, 2023). "Our in vitro and in vivo results show that high DEPDC1B expression promotes the EMT process in breast cancer cells." (PMID 37642235, 2023). "Our findings provide new insights into the carcinogenic mechanism of DEPDC1B, suggesting that DEPDC1B can be used as a potential therapeutic target for breast cancer." (PMID 37642235, 2023). "The purpose of this study was to investigate the role and mechanisms of DEPDC1B in breast cancer cells in vivo and in vitro." (PMID 37642235, 2023).
breast carcinoma (continued). "Scratch tests and Transwell assays showed that interference with DEPDC1B expression significantly inhibited the migration and invasion ability of breast cancer cells." (PMID 37642235, 2023). "To explore how DEPDC1B promotes the migration and invasion of breast cancer cells, we carried out protein mass spectrometry analysis and identified 414 binding proteins specific to DEPDC1B." (PMID 37642235, 2023). "Compared with normal tissues, DEPDC1B was highly expressed in breast cancer tissues, which was consistent with the results of the tissue microarray test." (PMID 37642235, 2023). "In summary, these results suggest that the activity of the wnt/β-catenin signaling pathway is inhibited after DEPDC1B interference in breast cancer cells." (PMID 37642235, 2023). "Our study reveals for the first time that DEPDC1B may be a potential therapeutic target for breast cancer patients." (PMID 37642235, 2023). "Therefore, we detected EMT indicators after interfering with DEPDC1B expression in breast cancer cells." (PMID 37642235, 2023). "In summary, our study further confirmed the tumor-promoting effect of DEPDC1B on breast cancer, which may be a potential therapeutic target for breast cancer." (PMID 37642235, 2023). "Furthermore, scratch assays, Transwell assays, immunofluorescence, and Western blotting were used to determine the biological behavior of breast cancer cells affected by DEP domain-containing protein 1B (DEPDC1B)." (PMID 37642235, 2023). "To further understand the role of DEPDC1B in breast cancer, we performed GSEA." (PMID 37642235, 2023). "The adherens junction pathway contains CTNNB1 (gene encoding β-catenin protein), which further supports that DEPDC1B may participate in the wnt/β-catenin signaling pathway in breast cancer cells." (PMID 37642235, 2023). "DEPDC1B is highly expressed in breast cancer, which is closely related to poor prognosis." (PMID 37642235, 2023). "Here, we studied the effect of DEPDC1B on the invasion and migration of breast cancer cells." (PMID 37642235, 2023). "In addition, we further analyzed the correlation between DEPDC1B expression and clinical factors of breast cancer." (PMID 37642235, 2023). "Finally, we found that in breast cancer cells DEPDC1B mediates the deubiquitination of β-catenin by USP5, stabilizes the β-catenin protein level, promotes nuclear translocation, activates the wnt/β-catenin signaling pathway, and ultimately promotes the transfer of breast cancer cells." (PMID 37642235, 2023). "Therefore, we hypothesized that in breast cancer cells DEPDC1B inhibits the ubiquitination of β-catenin by binding to USP5 and β-catenin." (PMID 37642235, 2023). "Therefore, our findings provide new insights into the carcinogenic role of DEPDC1B in breast cancer, suggesting that DEPDC1B may be a reliable prognostic factor and a potential therapeutic target for breast cancer." (PMID 37642235, 2023). "Importantly, we found that DEPDC1B mediates deubiquitination events in breast cancer cells." (PMID 37642235, 2023). "In summary, we can preliminarily confirm that DEPDC1B mediates the ubiquitin level of β-catenin by binding with USP5 and β-catenin in breast cancer cells." (PMID 37642235, 2023). "Immunofluorescence results showed that DEPDC1B, USP5, and β-catenin were colocalized in breast cancer cells." (PMID 37642235, 2023). "Coimmunoprecipitation (Co-IP) results showed that there was an interaction relationship between DEPDC1B and β-catenin and between DEPDC1B and USP5 in breast cancer cells." (PMID 37642235, 2023). "In summary, these results show that interfering with DEPDC1B expression blocks the EMT process and inhibits the migration and invasion of breast cancer cells." (PMID 37642235, 2023). "We found through bioinformatics analysis that DEPDC1B is the key DEG affecting the occurrence and development of breast cancer." (PMID 37642235, 2023).